NF1 (neurofibromin 1)
Diseases named in the same sentence as NF1 in open-access papers (continued):
Sharing a sentence is not in itself a finding about the gene and the disease.
neurofibroma (continued). "NF1 whole gene deletions of the NF1 gene are associated with a more severe clinical phenotype of NF1, including dysmorphic facial features, intellectual disability, congenital cardiac anomalies and increased numbers of cutaneous and subcutaneous neurofibromas (CNF) and plexiform neurofibromas (PNF)." (PMID 33951044, 2021). "However, the loss of NF1 is necessary but not sufficient for the progression of benign neurofibromas into MPNSTs." (PMID 32182803, 2020). "Moreover, three negative patients had a spinal form of NF1 and recently Santoro has reported p.Ser548Arg missense pathogenic variant in SOS1 gene in a patient with bilateral cervical and lumbar spinal lesions resembling plexiform neurofibromas and features suggestive of NF1." (PMID 32575496, 2020). "Therefore, while Nf1 DI transformations increase the probability that neurofibromas will occur, the mechanism(s) that actually triggers pNFs and cNF remains unknown." (PMID 31107888, 2019). "We previously demonstrated that STX3451 induces apoptosis in human NF1-deficient ST88 and S462 malignant peripheral nerve sheath tumour (MPNST) cell lines at very low concentration (300 nM), whilst arresting cell proliferation in an NF1−/−benign plexiform neurofibroma (PNF)." (PMID 31730023, 2019). "(2012) showed that an extremelyhigh burden of internal neurofibromas, characterised by >3000 ml tumour volumeas determined by whole-body MRI, was significantly more frequent in non-mosaictype-1 and type-2 NF1 microdeletion patientsthan in NF1 patients with intragenic lesions (13 vs. 1%)." (PMID 28213670, 2017). "The first G-P correlation is the association of NF1 missense mutations with spinal NF1 and the second one is an association between missense mutations in NF1 affecting codon p.Arg1809 without externally visible plexiform neurofibromas or cutaneous neurofibromas." (PMID 29311971, 2017). "Additionally, these data corroborate gene expression profiling of MPNST patient tissue samples by an independent group in which we found that BMP2 is up-regulated in MPNSTs as compared to other benign forms of neurofibromas that are typically heterozygous for Nf1." (PMID 27494873, 2016). "Currently there is no effective medical treatment for both neurofibroma and MPNST, although recent animal studies have suggested that MEK/ERK pathway could be a target for NF1-associated neoplasms, including plexiform neurofibroma but not MPNST." (PMID 27517146, 2016). "Although the second‐hit somatic NF1 mutation in the Schwann cells may trigger the formation of a neurofibroma in an NF1‐haploinsufficient microenvironment, the precise molecular interactions among the different cells in the development of neurofibromas remain poorly understood." (PMID 26432421, 2015). "Interestingly CENTA2 gene, alias ADAP2, was found to be expressed in neurofibromas and it has been candidate as a modifier gene contributing to a neurofibroma aberrant growth, both in number and in size, detected in NF1 microdeletion patients carrying a CENTA2 constitutional deletion." (PMID 23285209, 2012). "Furthermore, deletion of NF1 in the skin of CMV-CreERt2 NF1lox/− mice after topical application of tamoxifen led to local dermal neurofibroma formation, supporting the notion that the cell of origin for these tumors resides within the skin at close range of topical tamoxifen application." (PMID 22550514, 2012). "Importantly, we identified one neurofibroma (P082-1N) bearing a type-2 NF1 deletion, caused by a nonallelic homologous recombination (NAHR) between the SUZ12 gene and its pseudogene, which are both located adjacent to the NF1 low copy repeats." (PMID 21031597, 2011). "Pathologically, neurofibroma in NF-1 patients may be of the localized, plexiform, or diffuse type." (PMID 19568560, 2009). "A new systemic treatment option—selumetinib, a MEK inhibitor—has been approved for NF1 by the FDA (2020) and EMA (2021), which is mainly used for symptomatic, inoperable plexiform neurofibromas in children." (PMID 41598414, 2026).
neurofibroma (continued). "Preclinical studies of MPNST and neurofibroma have suggested investigation of MEK inhibitors in the treatment of Ras‐related diseases, including NF1." (PMID 41272396, 2025). "This tailored vector, AAV-NF, exhibits greatly reduced liver uptake, enhanced tumor targeting across various NF1-related MPNST, neurofibromas and glioma models, and therapeutic efficacy in xenografts of MPNST." (PMID 41022755, 2025). "Neurofibroma Schwann cells exhibit hyperactivation of RAS signaling, because the NF1 gene product normally accelerates the hydrolysis of active RAS-GTP to inactive RAS-GDP." (PMID 40992926, 2025). "For example, transgenic mice that lack both the PTEN and neurofibromatosis 1 (NF1) genes in SCs and SC precursor cells have demonstrated an augmented development of neurofibroma and high-grade peripheral nerve sheath tumors." (PMID 40940747, 2025). "An increased spatial affinity of neurofibromas to the DRG has been described in mouse models, and a case report of an NF1 patient confirmed tumour infiltration of the DRG." (PMID 40437318, 2025). "Although neurofibromas predominate in NF1, concepts from NF2 studies can be considered for DRG enlargement in NF1." (PMID 40437318, 2025). "Neurofibromatosis type 1 (NF1) is a genetic disorder driven by dysregulated RAS/MAPK signaling, leading to plexiform neurofibromas (PNs)." (PMID 40271285, 2025). "Neurofibromatosis 1 (NF1) is a rare genetic disease with multiple clinical manifestations, including plexiform neurofibromas (pNFs), which are benign tumors that grow along nerve sheaths." (PMID 40304934, 2025). "This interaction is characterized by increased migration of Nf1+/− mast cells, closely related to the overactivation of the Ras class IA-PI3K-Rac2 pathway and significant for the formation of neurofibromas during regeneration." (PMID 38651098, 2024). "Supporting the idea that PN SCP-like cells are tumor-initiating cells, Nf1-mutant embryonic SCPs and P75NGFR+EGFR+ SCP-like cells from PNs form neurofibromas on in vivo transplantation." (PMID 36134665, 2022). "We found that elevation of cAMP by either blocking the degradation of cAMP or by using a P2ry14 inhibitor diminished NF1-/- SCP self-renewal in vitro and neurofibroma SC proliferation in in vivo." (PMID 35311647, 2022). "Moreover, the occurrence of neurofibroma in normal individuals, as well as the recognition of patient subgroups with mosaic NF1 caused by postzygotic NF1 mutation, suggest that an NF1+/− environment may not necessarily be required for neurofibroma formation." (PMID 36139671, 2022). "One example of such discordance is Case 105, diagnosed as schwannoma but showing a SNP array profile that was indicative of a neurofibroma (duplication in 5q, a homozygous deletion of CDKN2A, and LOH at NF1)." (PMID 35318454, 2022). "The combination of a MEK inhibitor plus the SHP-2 inhibitor SHP099 was recently shown to be effective in models of NF1-MPNST and plexiform neurofibroma." (PMID 35625983, 2022). "Nf1-Arfflox/flox;PostnCre mice exhibited high expression of Ref-1 and p-STAT3 in MPNST as compared to plexiform and atypical neurofibroma precursor tumours." (PMID 33658640, 2021). "A study of 21 unrelated NF1 probands and 26 affected relatives shows that individuals with a 3-bp loss of a single amino-acid deletion at codon 992 (p.Met992del), 0.9% frequency in NF1 mutation individuals, present a mild clinical phenotype with CALMs and absence of neurofibroma manifestations." (PMID 34566848, 2021). "In conclusion, our findings suggested that SUZ12 loss potentiates the effects of NF1 mutations by amplifying Ras signaling through the ADCY1/cAMP/Rap1/ERK pathway and that SUZ12 may serve as a therapeutic and prognostic biomarker in NF1-associated neurofibromas." (PMID 34692515, 2021). "Plexiform neurofibromas can transform into malignant peripheral nerve sheet tumors (MPNST), which is one of the most common NF1-related malignancies." (PMID 33853649, 2021).
neurofibroma (continued). "In the case series, 22 patients had undergone an NF1 analysis performed on DNA from blood, CAL spots and plexiform neurofibromas." (PMID 33853649, 2021). "Neurofibromatosis 1 (NF1) is a neurocutaneous syndrome characterized by multiple café-au-lait macules, cutaneous neurofibromas or plexiform neurofibromas, iris Lisch nodules, axillary and inguinal freckling." (PMID 34164111, 2021). "In neurofibromas, Nf1+/- mast cells are essential to tumor formation due to critical SCF-mediated interactions with Nf1+/- Schwann cells." (PMID 32456131, 2020). "However, a comprehensive analysis of children has not yet been performed in order to ascertain whether an early (prepubertal) onset in growth of neurofibromas is significantly more prevalent in children with NF1 microdeletions as compared to children with intragenic NF1 mutations." (PMID 32533297, 2020). "On the other hand, there are sometimes neurofibromas and MPNST regions in the same tumour area of NF1-MPNST." (PMID 32606289, 2020). "Finally, to be remarked that regarding these genotype‐phenotype correlation‐ships is that our patient currently, had mild‐moderate phenotype of NF1‐disease with no plexiform neurofibromas, neither pheochromocytomas nor other tumor‐associated complications, and stable and controlled optic gliomas." (PMID 32533764, 2020). "Such depletion of COL3A1 also suppressed the growth of neurofibroma cells and DFAT cells derived from NF1 patients." (PMID 29666462, 2018). "Neurofibromatosis 1 (NF1) is an autosomal dominant disease characterized by café-au-lait macules, neurofibromas of any type, axillary and inguinal freckling and Lisch nodules in the iris." (PMID 25348553, 2014). "When Nf1 is biallelically inactivated in Schwann cells, GEM-grade 1 neurofibromas occur, but when phosphatase and tensin homolog (Pten) is also lost, these mice form numerous, high-grade PNSTs." (PMID 24681606, 2014). "Based on his history of NF1 and MPNST, this parapharyngeal space mass was suspected to be malignant degeneration of a neurofibroma, similar to his prior MPNST." (PMID 25548703, 2014). "RNA of high quality was available from 6 solid MPNST, 9 neurofibromas and several cell cultures (9 MPNST cell lines; NF1−/− Schwann cells and dermal fibroblasts)." (PMID 23139750, 2012). "After performing MMP analysis and/or MLPA analysis, we observed that in two neurofibromas (P004-7N, P082-1N) the deletion breakpoints were located very close to the low-copy repeats (NF1-REPs and the SUZ12 sequences) flanking the NF1 gene region." (PMID 21031597, 2011). "Some typical NF1 (MIM# 162200) features such as Lisch nodules of the iris, neurofibromas and central nervous system tumors were systematically absent." (PMID 21089071, 2011). "Furthermore, the finding of a sporadic neurofibroma and malignant melanoma occurring in a patient without NF-1 lends credence to the view that when these lesions occur in patients with NF-1, the association may be coincidental." (PMID 15363097, 2004). "Although our study focused on asymptomatic NF1 individuals who had not received any specific therapy, it is important to note that the emerging treatment selumetinib, used for plexiform neurofibromas, has been reported to negatively impact myocardial function." (PMID 41540280, 2026). "Here, we show that the vector, named as AAV-NF (K55), demonstrates marked tropism to NF1-related neurofibroma, MPNST and glioma in xenograft mouse models, with greatly reduced liver transduction, and achieves significant therapeutic efficacies in treating NF1 xenograft tumors." (PMID 41022755, 2025). "The p.Arg1830Cys variant usually results in a mild phenotype with major features consisting of pigmentary signs without neurofibromas or other NF1-related malignancies." (PMID 40410838, 2025). "A current limitation of our model is the absence of Cas9-directed induction of primary in vivo neurofibromas to directly compare MPNSTs to the pathological precursor lesion seen in patients with NF1." (PMID 40802750, 2025).
neurofibroma (continued). "Legius syndrome is the most important phenocopy of NF1, manifesting with CALMs without the development of neurofibromas or other NF1-related tumors." (PMID 40361417, 2025). "This suggests that CpG hypermethylation within the NF1 promotor is not likely to be the contributing genetic factor leading to the development of neurofibromas." (PMID 40843672, 2025). "Common pathological changes of NF1 include characteristic cutaneous café-au-lait spots, lack of pigment in the iris, optic glioma, neurofibroma, and distinctive changes in the sphenoid wing or long bone." (PMID 40697342, 2025). "Even when the conditions were separated officially in 1987 (with separate localisation of the genes), NF2-SWN remained classified as a neurofibromatosis despite the tumours pathognomonic for NF1, neurofibromas, not being a feature of NF2-schwannomatosis." (PMID 41160189, 2025). "Hemorrhagic events are therefore not uncommon; in a surgical series of neurofibroma resections, perioperative bleeding occurred in 46.8% of patients with NF-1." (PMID 40922847, 2025). "In an NF–1 genetically engineered mouse model of plexiform neurofibroma lacking BRAF alterations, tovorafenib showed no antitumor activity; moreover, although not statistically significant, tumor volume increased in 2 out of 12 mice (approximately 17%)." (PMID 40867225, 2025). "CRISPRi suppression of NF2 in NF1-mutant NF95.11b neurofibroma cells induced PAK1 phosphorylation (pPAK1) without significantly affecting pMEK, pERK, or pAKT compared to sgNTC." (PMID 38216572, 2024). "While multiple neurofibromas are commonly associated with hereditary syndromes like NF1 and NF2, isolated neurofibromas exist but are not well-described in the literature." (PMID 39070511, 2024). "Specifically, NF1 patients with NF1 exon 24 [19a] skipping typically exhibit a mild phenotype, characterized by the absence of severe NF1-specific clinical features, including neurofibromas." (PMID 39001468, 2024). "In Nf1+/- mice, nerve injury (crush or cut) to the sciatic nerve is not sufficient to promote plexiform neurofibroma in most cases." (PMID 38900740, 2024). "Nerve injury signals seem to be required for neurofibroma formation; NF1-/- myelinating Schwann cells did not form neurofibromas unless placed at a nerve injury site." (PMID 37817770, 2023). "Except for occasional small deletions affecting chromosome 17q encompassing the NF1 locus, benign neurofibromas (G4) and cutaneous neurofibromas (G6&7) did not harbor recurrent chromosomal aberrations." (PMID 37164978, 2023). "Currently, the sole FDA-approved drug treatment for NF1-associated inoperable plexiform neurofibromas is the MEK inhibitor selumetinib, which is indicated for the treatment of pediatric (but not adult) NF1-associated nerve sheath tumors." (PMID 38136356, 2023). "It is unclear how, or if, regulation of cAMP is relevant to neurofibroma initiation or growth but reducing cAMP drove formation of brain tumors in cells lacking Nf1." (PMID 35311647, 2022). "The other brother N03, harboring only the c.3314 + 2T > C splicing NF1 variants inherited from the mother, was also affected by SNF, as the proband, but the clinical phenotype was less severe: no internal or plexiform neurofibromas were present." (PMID 36612057, 2022). "Experts did not endorse renaming NF1 since virtually all individuals with NF1 develop neurofibromas and since the name is established by use and history." (PMID 34012067, 2021). "In animals lacking the Ras-related protein R-Ras2/TC21 (in addition to Nf1) the formation of neurofibromas was delayed, while that of sarcomas and brain tumors was accelerated." (PMID 33478130, 2021). "This autosomal-dominant inherited disease caused by SPRED1 mutation is indistinguishable from NF1, since it also produces café au lait macules and axillary or inguinal freckling but does not produce neurofibromas or malignant tumours in contrast to NF1." (PMID 34449562, 2021).